EPHA2 (EPH receptor A2)
Diseases named in the same sentence as EPHA2 in open-access papers (continued):
Sharing a sentence is not in itself a finding about the gene and the disease.
prostate carcinoma (continued). "For instance, EphA2 and EphB2 both promote tumor angiogenesis, but EphA2 is upregulated in prostate cancer, while EphB2 is downregulated." (PMID 33614496, 2020). "To further examine the effect of EphA2 on prostate-cancer cell migration, we used live-cell analysis of a scratch wound assay (IncuCyte S3, Sartorius, Göttingen, Germany)." (PMID 33023262, 2020). "While EphA1 abundance was decreased in prostate cancer cell lines, EphA2, EphA5, EphA6, EphA7, EphA8, and EphA10 levels were elevated in some of the prostate cancer cell lines as compared to the normal prostate cell line." (PMID 29682554, 2018). "The specific binding of SWL-coupled DNA trimers to PC-3 prostate cancer cells known to overexpress EphA2 was evaluated via ligand titration in in flow cytometry experiments." (PMID 30404153, 2018). "Here, the quantitative impact of SWL valency on binding, phosphorylation (key player for activation) and phenotype regulation in EphA2-expressing prostate cancer cells was demonstrated." (PMID 30404153, 2018). "Two different EphA2 binders were labeled with 64Cu, using a bifunctional MeCOSar chelator, and administered to mice bearing tumors from transplanted human prostate cancer cells, followed by PET/CT imaging." (PMID 26313909, 2015). "Expression of EphA2 protein in non-metastatic RCC (Caki-2 and A498), metastatic RCC cells (Caki-1 and ACHN), HEK-293 cells and prostate cancer cells (PC-3 and DU-145; positive controls of EphA2 expression) was evaluated by Western blot." (PMID 26177500, 2015). "In this context, the enhanced early adhesion to collagen I upon EphA2 activation is possibly involved in the adhesion of prostate cancer cells to bone matrix." (PMID 25644492, 2015). "These binders are specific to the EphA2 receptor, readily internalized into cells and can specifically target EphA2-expressing tumors in a human prostate cancer xenograft model." (PMID 26313909, 2015). "Collectively, these results demonstrate that EphA2 is involved in malignant cell behavior and is a potential therapeutic target in human prostate cancer." (PMID 24959216, 2014). "EphA2 overexpression in prostate cancer cells has been shown to increase migration via activation of Src and RhoA or via Akt in a ligand-independent manner." (PMID 24795148, 2014). "The results demonstrated that the LNCaP human prostate cancer cells that were transfected with pcDNA3.1(+) plasmid-mediated pcDNA3.1(+)-EphA2, markedly enhanced the cell growth and invasion in vitro." (PMID 24959216, 2014). "Elevated expression of androgen receptor, prostate specific antigen, cytokeratin 5, urokinase-type plasminogen activator and EphA2 correlated with dasatinib sensitivity in prostate cancer cell lines." (PMID 25594008, 2014). "Elevated ANXA1 mRNA expression was found in dasatinib sensitive breast and ovarian cell lines, whilst EphA2 mRNA was elevated in breast, ovarian and prostate cancer cell lines." (PMID 25594008, 2014). "An immunohistochemistry assay was also conducted to observe the effects of EphA2 in prostate cancer tissues." (PMID 24959216, 2014). "Activated EphA4 and EphA2 have been shown to trigger the activation of RhoA, which ultimately led to reinitiation of migration in a different direction in a prostate cancer cell line." (PMID 23738943, 2013). "In agreement with studies performed in prostate cancer cells, introduction of a dominant negative form of EphA2 into TC71 and RDES recapitulated most of the effects induced by CAV1 silencing." (PMID 23951165, 2013). "Here we show that CIL between prostate cancer cells is regulated by EphA receptors, specifically EphA2 and EphA4." (PMID 23495724, 2013). "We had previously identified cholanic acid as a competitive and reversible EphA2 antagonist able to disrupt EphA2-ephrinA1 interaction and to inhibit EphA2 activation in prostate cancer cells." (PMID 24152675, 2013).
prostate carcinoma (continued). "With the correlation of its expression with dasatinib sensitivity in cell lines, and being a target of the drug, EphA2 appears to be a strong candidate biomarker for dasatinib in prostate cancer." (PMID 18047674, 2007). "As a potent inhibitor against Abl, c-kit, PDGFRβ and, in particular, Src and EphA2, which have been shown to play important roles in prostatic tumorigenesis, dasatinib holds high promise as a potential treatment for prostate cancer." (PMID 18047674, 2007). "The most active of these derivatives was the l-Trp derivative (88, PCM126), which, at low micromolar concentrations, significantly outperformed LCA in terms of breaking the EphA2–ephrinA1 connection and decreasing EphA2 phosphorylation in prostate cancer cells." (PMID 41451409, 2025). "Preclinical studies indicated that treatment with MEDI-547 induced EphA2 degradation and internalization, decreased proliferation, increased apoptosis, and displayed antiangiogenic effects in endometrial and prostate cancer cells and mouse and rat orthotopic models." (PMID 39596256, 2024). "Additionally, EphA2 upregulation has been observed in liver, prostate cancer, glioblastoma, esophageal squamous cell carcinoma, ovarian cancer, and melanoma, with the highest levels detected in the most invasive tumor cells." (PMID 38811954, 2024). "In the PC3 human prostate cancer cell line, EphA2 coimmunoprecipitated with EphB2 via the ligand binding domain, showing a co-clustering of these receptors that may differentially affect the Eph-ephrin signaling landscape based on the present heteromers." (PMID 38984128, 2024). "In addition, the PPI dendron was conjugated via “click” chemistry to an EphA2-targeting antibody fragment that has been shown to target prostate cancer cells." (PMID 37631317, 2023). "The phage display method was used to discover the agonistic peptide SWL, which was demonstrated to activate EphA2 phosphorylation, and blocked major oncogenic pathways such as via Erk MAP kinases and Akt in PC3 prostate cancer cells, consistent with EphA2-mediated tumour suppression." (PMID 36830852, 2023). "EphA2 expression levels in several prostate cancer cell lines and patient-derived samples have been analyzed and evidenced that metastatic prostate cancer cells present EphA2 protein expression levels 10–100 fold higher than those in non-invasive prostatic epithelial cells." (PMID 36142306, 2022). "Higher EPHA2 expression has been previously associated with an increased probability of metastasis in several types of tumors, such as in non-small lung cell carcinoma (NSCLC), prostate cancer, and gastric adenocarcinoma." (PMID 35626181, 2022). "EPHA2 is highly expressed in breast, colorectal, esophageal, and prostate cancer." (PMID 33834064, 2021). "Indeed, suppression of EphA2 function in prostate cancer cells via overexpression of cytoplasmic deletion or kinase dead mutants impaired growth in bone." (PMID 33869989, 2021). "Therefore, various systems targeting EphA2 and other RTKs have been developed for the treatment of many solid tumors including prostate cancer." (PMID 33685469, 2021). "Moreover, previous studies reported that low-EphA2-expressing LNCaP prostate-cancer cells acquired increased invasion properties when transfected with EphA2." (PMID 33023262, 2020). "In addition, we also reported previously that earlier generations of agonistic EphA2-targeting-peptide mimetics can be used as carriers for targeted delivery of chemotherapy to breast, pancreatic, and prostate cancer." (PMID 33023262, 2020). "In the present study, we focused on targeting EphA2 in prostate cancer." (PMID 33023262, 2020). "In addition, Yeo and coworkers showed that fetal bovine serum at 1–5% induced VM formation in prostate cancer PC-3 cells as well as phosphorylation of EphA2." (PMID 31993365, 2019).
prostate carcinoma (continued). "This hypothesis is further supported by recent evidence showing that EPHA2-expressing prostate cancer cells gain an invasive advantage which was crucial to successfully colonize distant organs." (PMID 25025847, 2014). "Additionally, EphA2 was overexpressed in prostate cancer specimens and the expression of EphA2 was significantly associated with Gleason grade, total prostate-specific antigen, advanced clinical stage and lymph node metastasis." (PMID 24959216, 2014). "Our current studies show a significant downregulation of EphA2 in the metastatic cells and future studies to determine how EphA2 may contribute to the progression of prostate cancer." (PMID 23717685, 2013). "Doxazosin successfully inhibited AKT and ERK kinase activities in an EphA2-dependent manner, triggered EphA2 receptor internalization, suppressed migration of prostate, breast, and glioma cancer cells, reduced distal metastasis of human prostate cancer cells, and prolonged survival in mice." (PMID 39596256, 2024). "In addition, the SAM domain can control the function of the neighbouring kinase domain, since its removal from EphA2 increased tyrosine autophosphorylation in human prostate cancer cells and in a mouse skin carcinoma cell line, resulting in constitutive activity." (PMID 36830852, 2023). "In summary, both ephrinA1-Fc and 135H12 (at the highest concentration) can revert the pro-migration signaling associated with EphA2 expression in PC-3 prostate cancer cells, while cell proliferation was apparently not significantly affected by either treatment with 135H12 or by ephrinA1-Fc." (PMID 33023262, 2020). "EphrinA1-induced stimulation of EphA2 also leads to reduced ERK phosphorylation and suppresses growth of primary keratinocytes and prostate carcinoma cells." (PMID 38811954, 2024). "We compared two well-known EphA2 signaling responses, autophosphorylation on Y588 and downstream inhibition of AKT, in PC3 prostate cancer cells stimulated with different ligands." (PMID 35970390, 2022). "In prostate cancer and GBM, EphA2 S897 expression induced amoeboid motil-ity, which correlated with the induction of stemness markers, increased clonogenic poten-tial and tumour growth." (PMID 33572284, 2021). "To further assess if suppression of EphA2 signaling by agonistic agents can suppress tumor metastasis in vivo, we used the PC-3-GFP human prostate cancer cell line in an orthotopic xenograft model." (PMID 33023262, 2020). "We observed elevated tyrosine autophosphorylation levels upon deletion of the EphA2 SAM domain (EphA2ΔS) in DU145 and PC3 prostate cancer cells and a skin tumor cell line derived from EphA1/A2 knockout mice." (PMID 28338017, 2017). "The PKA-dependent activation of non-canonical EphA2 signaling has further been classified in aggressive pancreatic and prostate cancers." (PMID 39466050, 2024). "Experiments in cells showed that UniPR1331 inhibited phosphorylation of EphA2 in prostate cancer (PC3) cells without directly interfering with the kinase domain." (PMID 35215250, 2022). "Early studies identified EphA2 protein overexpression in prostate cancer cell lines with greater metastatic potential, while normal and benign prostate tumor cells showed weak or no staining with EphA2 antibody." (PMID 29682554, 2018). "In light of the decreased migration of prostate cancer cells upon stimulation of EphA2 with ephrin-A1, downregulation of ephrin-A1 in aggressive prostate cancers is not surprising." (PMID 29682554, 2018). "Several compounds have been repurposed to block EphA2 action as EphA2 antagonists, including Farnesoid X Receptor (FXR), GW4064, cilofexor, nidufexor, tropifexor, turofexorate isopropyl, and vonafexor, which demonstrated good preclinical results in tumor models, including prostate cancer." (PMID 39596256, 2024).
prostate carcinoma (continued). "However, LCA by targeting EphA2 LBD, is able to hamper receptor autophosphorylation induced by stimulation by ephrin A1-Fc in human prostate cancer cells and colon adenocarcinoma cell lines (PC3 and HT29) and avoids rounding and retraction of PC3 cells caused by EphA2 activation." (PMID 36142306, 2022). "However, to the best of our knowledge, the role that EphA2 plays in prostate cancer is not entirely clear." (PMID 24959216, 2014). "However, the effect of ephrin-A1 on EphA2 expressing cells may also be cell type-specific and transformation status-dependent: for instance, ephrin-A1 treatment inhibited proliferation of prostate cancer cells but failed to do so in fibroblasts." (PMID 33572284, 2021). "Moreover, while not all cell prostate cancers highly express EphA2 (indeed EphA2 does not seem to represent a reliable prognostic for prostate cancer from the protein-atlas database, we found that ADT treatment elevates EphA2 in prostate cancer cell lines CWR22Rv1 and ARCaPM." (PMID 33023262, 2020).
ovarian carcinoma (58 papers, 2006 to 2025). A malignant neoplasm originating from the surface ovarian epithelium. "In ovarian cancer and mammary tumourigenesis, EphA2 overexpression has been associated with increased microvascular density, indicating that EphA2 has a role in promoting angiogenesis in the tumour microenvironment." (PMID 30914876, 2018). "We identified miR‐520d‐3p as a tumor suppressor upstream of EphA2, which is associated with longer overall and relapse‐free survival time in ovarian cancer patients." (PMID 29024380, 2017). "The role of EphA2 in sustaining neoangiogenesis was also reported in ovarian carcinoma, where EphA2 was associated with high expression of vascular endothelial growth factor (VEGF-a) and vascular endothelial cadherin (VE-cadherin) upregulation at both mRNA and protein levels." (PMID 39596256, 2024). "Moreover, eighty-nine patient derived ovarian tumors and four ovarian cancer cell lines have been analyzed and results point out that EphA2 expression is linked to aggressive characteristics of ovarian carcinoma." (PMID 36142306, 2022). "EPHA2 inhibition by dasatinib or a novel immunoconjugate containing an anti-EPHA2 monoclonal antibody linked to a chemotherapeutic agent, shows antitumor activity against EPHA2-positive ovarian cancer cell lines and mouse tumor models." (PMID 21962244, 2011). "The role of MEK in the regulation of EphA2 was also confirmed in another ovarian cancer cell line, PEO1 cells treated with U0126." (PMID 41130297, 2025). "There is an accumulating body of evidence that EphA2 is abundantly expressed in ovarian cancer and is involved as an active participant in tumorigenesis." (PMID 37612696, 2023). "Only three out of ten MPAS genes (PHLDA1, EPHA2, and DUSP4) displayed reproducible associations with baseline levels and changes in MEK/ERK activity across most ovarian cancer model systems and clinical samples." (PMID 36362153, 2022). "In ovarian cancer, VEGF-A has been linked to VM formation by elevating the expression of MMP-9, MMP-2, VE-cadherin, and EphA2." (PMID 35747793, 2022). "Levels of PHLDA1, DUSP4, and EPHA2 expression were also significantly associated with baseline levels of MEK/ERK pathway activity in multiple human ovarian cancer cell lines and ovarian cancer patient samples available from the TCGA database." (PMID 36362153, 2022). "We evaluated possible associations between the expression of PHLDA1, SPRY4, EPHA2, and DUSP4 and MEK/ERK pathway activity in 20 ovarian cancer cell lines." (PMID 36362153, 2022). "Targeting EphA2 is especially attractive in ovarian cancer, in which overexpression is present in over 75% of cases." (PMID 34691070, 2021). "Inhibition or knockdown of RSK1/2 strongly reduced EphA2-S897 phosphorylation in favor of the ligand-induced tumor-suppressive tyrosine phosphorylation, thus triggering downregulation of EphA2 and reverting platinum resistance of the ovarian cancer cells." (PMID 33572284, 2021). "In silico assays revealed a miR-200a binding site at EphA2 3′UTR; this observation was confirmed in SKOV3 ovarian cancer cells, where a direct binding of miR-200a to EphA2 3′UTR was observed through luciferase assays." (PMID 31612116, 2019). "This suggests that VEGF-A interacts with the VE-cadherin/EphA2/MMP-2/Ln5γ2 axis in the regulation of VM in ovarian cancer." (PMID 31612116, 2019). "An inverse correlation between mRNA and protein EphA2 levels and miR-200a expression was observed in ovarian cancer samples, suggesting a direct regulation among them." (PMID 31612116, 2019). "Arg957 (corresponding to Arg958 of mouse EphA2 SAM), which is found to be mutated to Cys in patients with ovary carcinoma, is located in the SAM-SAM binding interface." (PMID 29749928, 2018).